PTH (parathyroid hormone)
Diseases named in the same sentence as PTH in open-access papers (continued):
Sharing a sentence is not in itself a finding about the gene and the disease.
diabetes (continued). "A backward elimination method adjusting for potential confounders namely age, gender, race, BMI, smoking habits, diabetes status, hypertension status, eGFR, serum triglyceride, LDL cholesterol, HDL cholesterol, calcium, phosphate, and PTH levels was applied." (PMID 27756244, 2016). "Gender, diabetes, glomerular filtration rate (GFR), hemoglobin, PTH, markers of mineral metabolism, inflammation, iron status and nutrition were variables of adjustment in univariate and multivariate analysis." (PMID 25113067, 2015). "Serum Mg was inversely correlated with serum Ca (P = 0.023) and positively correlated with serum parathyroid hormone (PTH) (P = 0.020), alkaline phosphatase (P = 0.044), and phosphate (P = 0.040) in the CKD patients with diabetes." (PMID 26273297, 2015). "In multivariate linear regression with PTH as the continuous dependent variable, age (b=-3.61, p<0.001), diabetes (b=-79.76, p<0.001), Ca (b=-145.13, p<0.001), and PO4 (b=165.76, p<0.001) were independent predictors of PTH." (PMID 23865464, 2013). "Patients with very low parathyroid hormone (PTH) level had a higher mortality rate after adjustment for age, gender, diabetes, and dialysis vintage." (PMID 23936653, 2013). "Phosphorus remained a significant risk factor for CAC even after adjustment for multiple variables such as age, gender, diabetes, hypertension, FGF23 level, and PTH concentration." (PMID 22590632, 2012). "Patients with IL-8 serum concentrations ≥ 40.26 pg/mL had higher systolic and diastolic blood pressure before dialysis; more history of hypertension, diabetes, coronary artery disease, and heart failure; and higher serum concentrations of IL-6, IAA, TGFβ, and lower PTH." (PMID 41003499, 2025). "In a study that included 40,538 hemodialysis patients, those without diabetes had considerably greater PTH levels than those with diabetes." (PMID 39791168, 2025). "PD patients with a history of diabetes had lower Ln_PTH, Alb, and corrected Ca but were older than those without diabetes (P<0.05)." (PMID 39791168, 2025). "By incorporating biochemical markers such as PTH, ALP, and estrogen levels into our analysis, our study also provides a more comprehensive metabolic profile of bone health in postmenopausal women with diabetes." (PMID 40428747, 2025). "The non-dialysis patients with diabetic history also had lower levels of Ln_PTH than those with diabetes, but the difference was not statistically significant." (PMID 39791168, 2025). "Patients with PTH >600 pg/mL at 12 months of HD were younger, and more likely to be non-white, with a lower prevalence of diabetes and private paying source." (PMID 40525801, 2025). "Diabetes history was absent and glycated hemoglobin normal, but serum calcium was severely low, with abnormally high parathyroid hormone." (PMID 37664540, 2023). "Our data reinforce the evidence that survival declines with increasing age, but do not corroborate previous results that point to diabetes, hypoalbuminemia, inadequacy of dialysis, anemia and higher PTH levels as predictors of mortality." (PMID 35510838, 2023). "Obese women have higher BMD and lower 25(OH)-vitamin D values (and higher PTH) than non-obese, without diabetes." (PMID 35789433, 2022). "In addition, with the increase in sedentary time, the duration of diabetes increased, HbA1c increased, the levels of N-MID and 25(OH)D decreased, and the levels of β-CTX, TP1NP and PTH increased (p < 0.001)." (PMID 35033170, 2022). "Sclerostin levels increase with age and PTH was shown to be an independent determinant of sclerostin in patients without diabetes." (PMID 36190530, 2022). "We included all the variables with a p-value less than 0.05 into the multivariate logistic regression model (including monthly frequency of HD, sex, diabetes, BUN, Scr, TG, LDL-c, HDL-c, phosphorous, iron, PTH, vitamin D, NT-proBNP, hemoglobin, CRP, Kt/V urea, and ferritin)." (PMID 36562038, 2022).
diabetes (continued). "A state of relative hypoparathyroidism has been suggested to contribute to low bone turnover in patients with diabetes: Reduced serum levels of CTX and TRAP5b have been found to correlate with low levels of parathormone (PTH) but potential implications of serum magnesium levels were not addressed." (PMID 36190530, 2022). "As expected, total 25(OH)D and PTH were significantly and inversely correlated across racial/ethnic groups among all women without diabetes." (PMID 34531372, 2021). "We investigated the association between serum 25OHD, Ca and PTH levels and the risk of CAD in patients with diabetes, which has, as far as we know, not been examined previously using the MR approach." (PMID 34602077, 2021). "Although bone responsiveness to PTH decreases in patients on chronic HD and those with diabetes, the percentage of patients with diabetes was not significantly different among the three categories." (PMID 34372813, 2021). "Our estimated partial Spearman’s correlations show that creatinine and hs-CRP, as well as fasting glucose and insulin, were inversely correlated with 25(OH)D and positively correlated with PTH among individuals without diabetes." (PMID 34531372, 2021). "However, after adjusting for age, BMI, blood pressure, diabetes duration, treatment for DM, smoking, alcohol intake, family history of DM, BUN, Cr, eGFR, FBG, Ca, ALT, AST, ALP, PTH, and 25(OH)D, this positive correlation disappeared." (PMID 32903642, 2020). "Our observation demonstrated that EMPA caused a slight but significant increase in serum phosphate and PTH concentrations and is in line with similar observations in patients with or without diabetes." (PMID 32185580, 2020). "No patient was diagnosed with diabetes and the percentages of patients with impaired glucose tolerance and elevated parathyroid hormone were similar in both groups." (PMID 30834265, 2019). "The mean physical activity score, Ca, PTH, urine pH and the prevalence of diabetes were not different between two groups." (PMID 28491855, 2017). "Patients with high GGT levels had a higher prevalence of diabetes mellitus, anti-HCV Ab positivity, had higher serum levels of AST, ALT, ALP, ferritin and hsCRP, and had lower diastolic blood pressure and lower serum levels of phosphorous and intact PTH." (PMID 26376075, 2015). "A cross-sectional study also has shown that type 2 diabetes patients have lower levels of bone resorption markers and PTH compared with subjects without diabetes." (PMID 26273297, 2015). "Coronary artery calcification was predicted by age, gender, and diabetes, but not by parameters related to renal function, including eGFR, calcium, phosphorous, i-PTH, hemoglobin, and albumin." (PMID 26042415, 2015). "A direct relationship between a higher serum calcium concentration and increased RR of death was observed across the entire spectrum of serum calcium values examined, independent of age, race, sex, diabetes status, vintage, phosphorus, and PTH." (PMID 23525083, 2013). "Serum PTH levels were lower in patients with diabetes compared with those without diabetes below 80 years (p<0.001)." (PMID 23865464, 2013). "Using these categories, we observed decreasing PTH levels with increasing age in both diabetes and non-diabetes subgroups (two-way ANOVA, p<0.001 for all comparisons; p=0.138 for the interaction diabetes × age)." (PMID 23865464, 2013). "Groups with and without fractures were balanced for gender, diabetes, BMI, eGFR, serum calcium level, serum phosphate level, intact PTH level, ALP level, and urinary NTX level." (PMID 23013306, 2012). "This study demonstrates the negative effect of Mg and diabetes on Ln_PTH levels in CKD5 patients." (PMID 39791168, 2025). "Our results support this hypothesis, as individuals with diabetes with FN OP and individuals without diabetes with LS OP exhibited significant PTH levels, consistent with findings from previous studies." (PMID 40428747, 2025).
diabetes (continued). "Clinicians should note that low VD levels do not accompany elevated PTH in patients with diabetes, and elevated PTH may indicate poorly controlled T2DM." (PMID 40313432, 2025). "It has been noted that PTH mitigates the negative impact of glucocorticoids on osteoblast survival and the Wnt signaling pathway, and treatment with PTH has been shown to inhibit osteoblast apoptosis in bones affected by diabetes." (PMID 38474370, 2024). "Nevertheless, PTH and both doses of ABL decreased bone mRNA Sost expression and ABL also reduced circulating sclerostin protein levels, suggesting a potential role of Sost/sclerostin downregulation in the anabolic function of the PTH1R ligands in the context of diabetes." (PMID 37076478, 2023). "Serum 25OHD, Ca and PTH levels may not serve as a target for prevention or treatment of CAD in patients with diabetes." (PMID 34602077, 2021). "Furthermore, the non-attendees at follow-up had longer diabetes duration but lower diastolic blood pressure and lower levels of PTH, 25(OH)D3, and creatinine (p < 0.05)." (PMID 32440752, 2020). "Furthermore, in two large cohort studies, cinacalcet was shown to reduce overall and CV mortality in adult patients with PTH > 300 pg/mL and adult patients with moderate sHPT (PTH 300–599 pg/mL), younger age, and without diabetes." (PMID 32367309, 2020). "PTH administration in periodontitis condition did not result in a significant increase in the area of the alveolar bone compared to the P group, but PTH administration in periodontitis with diabetes condition elicited its improvement compared to the DP group." (PMID 29544500, 2018). "In diabetes patients with complications, there were significant negative correlation between OC and CTX with estimated-glomerular filtration rate (e-GFR) and also positive correlation between each bone marker (OC and CTX) and PTH levels (p = 0.0001) and BUN (p = 0.0001)." (PMID 27826545, 2016). "Despite this, we found no significant impact on PTH levels by diabetes status in our study." (PMID 26078787, 2015). "Considering the increasing evidence that suggests low bone formation in diabetes, osteoanabolic therapies such as PTH-based drugs are attractive but this hypothesis has not been substantiated by clinical studies yet." (PMID 25140176, 2014). "The diabetes prevalence difference might be of particular interest since diabetic patients with MS have lower PTH levels than MS-subjects without diabetes." (PMID 21306649, 2011). "PTH values were more variable in the diabetic animals, but no statistical difference was found between control and diabetic mice at 10, 15, or 18 weeks after the onset of diabetes." (PMID 21747824, 2011). "Notably, our subgroup analysis showed a stronger PTH–WMH link in patients with diabetes than in those without, suggesting that future studies could examine this relationship in larger diabetic samples." (PMID 41050279, 2025). "Patients with diabetes mellitus (DM) had lower levels of Ln_PTH in PD (P<0.05) and non-dialysis (P>0.05) patients." (PMID 39791168, 2025). "Serum bone formation (P1NP, total osteocalcin), bone resorption (CTX) markers, and parathyroid hormone (PTH) were not significantly different between postmenopausal women with T1D and controls without diabetes." (PMID 38025041, 2023). "A recent study showed that accumulation of uraemic toxins such as parathyroid hormone and β2-microglobulin correlates closely with GCC impairment in CKD patients without diabetes or dialysis." (PMID 37008921, 2023). "The relationship with age, gender, diabetes, systolic BP (SBP), diastolic BP (DBP), HDL/cholesterol ratio, BAP, and PTH were not significant in univariate analysis." (PMID 31519772, 2019). "Adding other factors including the presence of diabetes, serum creatinine, MDRD-4 eGFR, urinary ACR, serum C-reactive protein (CRP), calcium, phosphate, PTH, RANKL, OPG and MGP did not improve the model significantly." (PMID 28320782, 2017).
diabetes (continued). "The objective of this study was to evaluate the impacts of serum Mg levels on PTH and bone mineral metabolic parameters among CKD patients with or without diabetes." (PMID 26273297, 2015). "Additionally, we explore the role of key metabolic and hormonal markers, including PTH, ALP, and estrogen, to elucidate their contributions to bone health in postmenopausal women with and without diabetes." (PMID 40428747, 2025). "Moreover, differences in the correlations between serum Mg with Ca, PTH, and bone mineral metabolism between CKD patients with and without diabetes have not been fully explored." (PMID 26273297, 2015). "Further prospectively designed and supplementary studies with a large sample size may help us to reveal the effects of the Mg status on PTH and bone mineral metabolism in CKD patients with or without diabetes." (PMID 26273297, 2015).
hypophosphatemia (256 papers, 2008 to 2026). Lower than normal levels of phosphates in the circulating blood. "It is frequently associated with hypophosphatemia and hypomagnesemia and is exacerbated by a marked decline in PTH levels." (PMID 41568160, 2026). "Hypophosphatemia (HypoP) (P < 2.5 mg/dL) was present in 14.3% of patients and was associated with higher parathyroid hormone, calcium, and alkaline phosphatase levels, and lower vitamin D levels (all p < 0.0001)." (PMID 41509939, 2025). "This raises the questionwhether persistent hypophosphatemia after FCM was caused by “inappropriately normal FGF23” orby “inappropriately normal PTH”?" (PMID 38746050, 2024). "Elevated FGF23 levels cause phosphaturia and hypophosphatemia by the direct suppression of NaPi-2a and NaPi-2c cotransporters in proximal tubular cells, or by affecting parathyroid hormone (PTH) activity." (PMID 39687707, 2024). "Diagnosis revolves around aprofound and persistently low calcium level of less than 2.1 mmol/L for more than 4days postoperatively, along with hypophosphatemia and normal PTH levels.Hypomagnesemia and hypocalciuria are often associated." (PMID 39700332, 2024). "Bellini and colleagues reported the case of a 64 years-old patient with mRCC treated with sorafenib (400 mg b.i.d. orally), who developed hypophosphatemia after 1 month of treatment associated with a decrease in serum calcium and elevated PTH levels." (PMID 36672478, 2023). "Among TKI used in RCC, sunitinib and sorafenib can cause hypophosphatemia with increased PTH levels and low-normal serum calcium levels." (PMID 36672478, 2023). "MBD after KT was manifested as an increased prevalence of hypophosphatemia and bone loss, persistent 25(OH)vitD deficiency, and partially decreased PTH and bone turnover markers (BTMs)." (PMID 37183797, 2023). "In this group, hypophosphatemia was associated with elevated PTH levels, low-to-normal serum calcium levels, and decreased biochemical markers of both bone formation and resorption." (PMID 36672478, 2023). "Hypophosphatemia due to renal phosphate loss in a setting of normal or low PTH is an accepted indication for FGF23 measurement." (PMID 35665817, 2023). "This approach was originally proposed by Penido and Alon and is based on the underlying mechanisms of hypophosphatemia, i.e., i) elevated levels of the phosphaturic hormone PTH, ii) inadequate intestinal phosphate absorption, and iii) renal phosphate wasting." (PMID 34910242, 2022). "Hypophosphatemia associated with renal phosphate wasting, normal serum levels of calcium, parathyroid hormone, and 25-hydroxyvitamin D represents the main biochemical sign in affected patients." (PMID 34421819, 2021). "Excess fibroblast growth factor 23 (FGF23), excess PTH, and an increase in extracellular calcium cause hypophosphatemia by lowering the maximum renal phosphate reabsorption threshold (TmP/GFR)." (PMID 33615106, 2021). "Stage 2 is characterized by the normalization of circulating calcium, while parathyroid hormone and alkaline phosphatase become elevated causing hypophosphatemia, and this hypophosphatemia is thought to cause a failure in chondrocyte apoptosis." (PMID 34068971, 2021). "Hypophosphatemia is a common finding in KTRs, especially in those with immediate graft function and a high pre-transplant serum PTH level due to the significant urinary phosphorus loss driven by the effects of high levels of PTH and FGF-23." (PMID 33919913, 2021). "At the age of 18 months, a renal ultrasonography showed a bilateral nephrocalcinosis grade II, associated to hypercalciuria, hypophosphatemia, increased 1,25 OH vitamin D with abnormally low parathyroid hormone level (PTH)." (PMID 33952337, 2021). "The association of hypophosphatemia, normal serum levels of calcium and PTH with the evidence of clinical and radiological signs of rickets is suggestive for the diagnosis of XLH." (PMID 34421819, 2021).